DROSHA (drosha ribonuclease III)
Diseases named in the same sentence as DROSHA in open-access papers (continued):
Sharing a sentence is not in itself a finding about the gene and the disease.
endometriosis (2 papers, 2023 to 2025). The growth of functional endometrial tissue in anatomic sites outside the uterine body. "Furthermore, miR-93-5p has been identified through in silico analysis as a negative regulator of DROSHA, a crucial protein for miRNA production whose alterations can affect gene regulation and have been implicated in various diseases, including endometriosis." (PMID 40305232, 2025). "Nine miRNAs (miR-128-3p, miR-27a-3p, miR-27b-3p, miR-181a-5p, miR-181b-5p, miR-452-3p, miR-216a-5p, miR-216b-5p, and miR-93-5p) were experimentally verified as negative regulators of DROSHA through in silico analyses and, according to the literature, have been associated with endometriosis." (PMID 36983035, 2023). "In light of these reports, we questioned whether deficient DROSHA expression in endometriosis MenSCs could affect the maturation of a set of miRNAs that depend on the canonical and non-canonical (DICER-independent) pathways." (PMID 36983035, 2023). "Because DROSHA is essential for miRNA maturation, our findings may justify the identification of different profiles of miRNAs with DROSHA-dependent biogenesis in endometriosis." (PMID 36983035, 2023). "Because DROSHA is part of the multiprocessor complex and is essential for the nuclear processing of pri-miRNA maturation, our findings may justify the identification of different profiles of miRNAs due to compromised DROSHA-dependent biogenesis in endometriosis." (PMID 36983035, 2023). "In addition, miR-128-3p, miR-27a-3p, miR-27b-3p, miR-181a-5p, miR-181b-5p, miR-452-3p, miR-216a-5p, miR-216b-5p, and miR-93-5p, which have been associated with endometriosis, were identified through in silico analyses as negative regulators of DROSHA." (PMID 36983035, 2023). "However, the reasons and mechanisms for the DROSHA changes in endometriosis and their impact on mesenchymal stem cells in the disease are unknown." (PMID 36983035, 2023). "Our goal, therefore, was to evaluate whether the gene expressions of DROSHA, DGCR8, XPO5, DICER, and AGO1 to AGO4 are differential in MenSCs of women with endometriosis." (PMID 36983035, 2023).
epilepsy (2 papers, 2022 to 2025). A brain disorder characterized by episodes of abnormally increased neuronal discharge resulting in transient episodes of sensory or motor neurological dysfunction, or psychic dysfunction. "In this regard, the authors find that interactions of circEFCAB2 with miR-485-5p and circ-DROSHA with miR-1252-5p were highly correlated with the expression of epilepsy-associated genes CLCN6 and ATP1A2, respectively." (PMID 35328484, 2022). "These circRNAs arise from exons and could regulate their host genes: up-regulation of EFCAB2 could influence calcium ion binding and, therefore, may concur to epilepsy; the loss of DROSHA causes neuronal and glial abnormality and seizures." (PMID 35328484, 2022).
hepatocellular carcinoma (2 papers, 2023). A malignant tumor that arises from hepatocytes. "In this sense, circulating miR-1246/U2 is upregulated in hepatocellular carcinoma and constitutes a non-canonical miRNA that generates from the U2 snRNA in a DROSHA and DICER independent manner." (PMID 37237528, 2023).
idiopathic pulmonary fibrosis (2 papers, 2019 to 2020). Idiopathic pulmonary fibrosis (IPF) is a nonneoplastic pulmonary disease that is characterized by the formation of scar tissue within the lungs in the absence of any known cause. "Here we demonstrate that DROSHA contributes to AIM2 inflammasome activation-dependent lung inflammation during idiopathic pulmonary fibrosis." (PMID 31434287, 2019). "Our findings suggest DROSHA-dependent AIM2 inflammasome activation contributes to pulmonary fibrosis." (PMID 31434287, 2019). "We investigated the role of DROSHA in alveolar macrophages in a mouse model of bleomycin-induced pulmonary fibrosis." (PMID 31434287, 2019). "Since DROSHA and AIM2 expression levels were elevated in alveolar macrophages during lung fibrosis, we next investigated the function of DROSHA during AIM2 inflammasome activation in alveolar macrophages." (PMID 31434287, 2019). "Similarly, the protein levels of DROSHA were elevated in alveolar macrophages in a mouse model of bleomycin-induced pulmonary fibrosis." (PMID 32121297, 2020). "We analyzed whether the DROSHA expression levels were elevated in alveolar macrophages of lung tissues from a mouse model of bleomycin-induced pulmonary fibrosis using immunohistochemistry staining." (PMID 31434287, 2019). "However, the mechanisms by which DROSHA affects the lung inflammation during idiopathic pulmonary fibrosis (IPF) remain unclear." (PMID 31434287, 2019). "Recently, we have reported for the first time that the protein expression of DROSHA was increased in alveolar macrophages of patients with IPF and mice with bleomycin-induced pulmonary fibrosis." (PMID 32121297, 2020). "We also found that DROSHA and AIM2 protein expression were increased in alveolar macrophages of lung tissues in a mouse model of bleomycin-induced pulmonary fibrosis." (PMID 31434287, 2019). "Here, we show that both DROSHA and AIM2 protein expression are significantly elevated in alveolar macrophages of patients with IPF and a mouse model of bleomycin-induced pulmonary fibrosis." (PMID 31434287, 2019). "Here, we demonstrate that DROSHA regulates the absent in melanoma 2 (AIM2) inflammasome activation during idiopathic pulmonary fibrosis (IPF)." (PMID 31434287, 2019). "Although not yet fully completed, our study provides the role of DROSHA in AIM2 inflammasome-dependent lung inflammation in the pathogenesis of pulmonary fibrosis." (PMID 31434287, 2019). "To investigate the role of DROSHA during lung fibrosis in patients with IPF, we analyzed whether the DROSHA protein levels were elevated in lung tissues from patients with IPF." (PMID 31434287, 2019).
laryngeal carcinoma (2 papers, 2018 to 2023). Carcinoma that arises from the laryngeal epithelium. "In contrast, DROSHA*rs6877842 carriers were three times more likely to develop CLL (OR = 3.15) and were associated with a 46% decreased risk in laryngeal cancer (OR = 0.56)." (PMID 36672288, 2023). "In stratified analysis, correlations of DROSHA rs10719 and rs6877842 SNPs were observed in Asian and laryngeal cancer subgroups, respectively." (PMID 29654164, 2018).
leprosy (2 papers, 2022 to 2023). Leprosy is a chronic infectious disease affecting primarily the skin and peripheral nervous system. "The rs639174 variant (DROSHA) is an intronic SNP with a recognized role in transcriptional regulation, and in our study, the CC genotype of this polymorphism, in a dominant model, was associated with protection against leprosy per se and MB." (PMID 36142557, 2022). "Interestingly, the TT genotype of the SNP rs10035440 (DROSHA), which also plays an important role in the splicing and transcriptional regulation of the DROSHA gene, was associated with the risk of developing leprosy per se and MB in the dominant model." (PMID 36142557, 2022). "Comparing genotypes of patients grouped according to MB clinical form with the control group, SNPs rs639174 (DROSHA), rs636832 (AGO1) and rs4143815 (miR570) were associated with a reduced risk of MB leprosy using a dominant model." (PMID 38116294, 2023). "This study investigated the association of twenty-five genetic variants in miRNAs and miRNA machinery-related genes (DROSHA and AGO1) with leprosy susceptibility in a population from the Amazon region, northern Brazil." (PMID 36142557, 2022). "SNPs rs639174 (DROSHA) and rs636832 (AGO1) were also associated with decreased risk of leprosy in the dominant model (p = 0.02; OR = 0.45; 95%CI = 0.23–0.89 and p = 0.01; OR = 0.45; 95%CI = 0.23–0.89, respectively)." (PMID 36142557, 2022).
lung adenocarcinoma (2 papers, 2021 to 2023). A carcinoma that arises from the lung and is characterized by the presence of malignant glandular epithelial cells. "In turn, such an analysis shows an insignificantly higher relative methylation of DROSHA in samples from patients with lung adenocarcinoma compared to the control (p = 0.1020)." (PMID 34885248, 2021).
male idiopathic infertility (2 papers, 2011 to 2023). "Real time PCR showed that two SNPs (rs10719, rs642321) in the DROSHA gene and one SNP (rs12323635) in the DICER gene were associated with male idiopathic infertility in Han Chinese population." (PMID 37924131, 2023).
schizophrenia (2 papers, 2021 to 2024). A major psychotic disorder characterized by abnormalities in the perception or expression of reality. "Specific attention is given to the impact of SNPs in DICER, DROSHA, and DGCR8, as well as the potential for changes in DRD2 gene expression driven by miR-9 and miR-326, heightening the likelihood of Schizophrenia development." (PMID 38343691, 2024).
adrenocortical tumors (1 paper, 2013). "We also tested the predictive potential for TARBP2 and DROSHA to detect ACCs among the 45 potentially malignant adrenocortical tumors after exclusion of tumors with sizes ≤3 cm and the seven patients presenting metastases at diagnosis." (PMID 23671264, 2013). "We analyzed the mRNA expression levels of five miRNA-processing genes (DROSHA, DGCR8, DICER, TARBP2, and PRKRA) in 73 adrenocortical tumors and nine adrenal cortices using RT-qPCR." (PMID 23671264, 2013). "Adrenocortical tumor patients were divided into high or low mRNA levels of TARBP2, DICER, and DROSHA according to their median expression levels." (PMID 23671264, 2013).
adult T cell Leukemia (1 paper, 2023). "Interestingly, the authors measured DROSHA, DGCR8, XPO5, DICER1, AGO2, and AGO3 mRNA expression, and only DICER1 mRNA was differently expressed in CD8+ T-cell–depleted PBMCs from HTLV-1 asymptomatic carriers when compared to patients with acute adult T cell Leukemia." (PMID 37243263, 2023).
chronic hepatitis B (1 paper, 2023). "Another study found that patients with chronic hepatitis B who had high hepatitis B virus loads had reduced mRNA levels of DROSHA, DICER1, and AGO2 compared with patients with low virus loads." (PMID 37243263, 2023).
COVID-19 (1 paper, 2023). A disease caused by infection with severe acute respiratory syndrome coronavirus 2. "mRNA levels of AGO2, DICER1, DGCR8, DROSHA, and Exportin-5 (XPO5) were measured by quantitative reverse-transcription polymerase chain reaction (RT-qPCR) in nasopharyngeal swab specimens from patients with COVID-19 and controls, as well as in cells infected with SARS-CoV-2 in vitro." (PMID 37243263, 2023). "Measured mRNA levels of AGO2, DICER1, DGCR8, DROSHA, and XPO5 were not significantly different in nasopharyngeal swab specimens of severe COVID-19 patients compared to non-severe COVID-19 patients or controls." (PMID 37243263, 2023). "Our data showed that the mRNA expression levels of AGO2, DICER1, DGCR8, DROSHA, and XPO5 were not significantly different in patients with severe COVID-19 when compared to patients with non-severe COVID-19 and controls." (PMID 37243263, 2023).
depression (1 paper, 2024). "The aim of our research was to assess the relationship between the occurrence of depression and single-nucleotide polymorphisms (SNP) in the following genes in the Polish population: DROSHA (rs6877842; rs10719) and XPO5 (rs11077)." (PMID 39596271, 2024). "A correlation with depression was observed in the rs10719/DROSHA, rs6877842/DROSHA, and rs11077/XPO5 polymorphisms." (PMID 39596271, 2024). "The T/G genotype of the rs11077/XPO5 polymorphism and the A/G genotype of the rs10719/DROSHA polymorphism increased the risk of depression, whereas the G/C and C/C genotypes of the rs6877842/DROSHA polymorphism lowered the risk of depression." (PMID 39596271, 2024). "Findings indicated that within our patient cohort, the risk of depression is increased by polymorphic variants of the rs10719/DROSHA and rs11077/XPO5 genes and lowered by rs6877842/DROSHA." (PMID 39596271, 2024). "We believe that SNPs in DROSHA (rs10719 and rs6877842) and XPO5 (rs11077) are associated with an increased risk of depression." (PMID 39596271, 2024). "In our research, we sought to determine whether specific single-nucleotide polymorphisms (SNPs) in genes associated with nuclear microRNA processing, namely, DROSHA (rs6877842; rs10719) and XPO5 (rs11077), are linked with depression risk in the Polish population." (PMID 39596271, 2024). "Such an approach may provide valuable insights into whether these specific SNPs in DROSHA and XPO5 contribute to recurrent episodes of depression, thereby offering insights into the genetic factors that influence the likelihood of relapse." (PMID 39596271, 2024).
diabetes (1 paper, 2021). "A thorough investigation of the role of MDM2 on DROSHA might bring new insight into the pathological process through which diabetes supports the loss of angiogenic capacity in these two tissues." (PMID 33801773, 2021). "Further investigations are required to establish whether glucose-dependent downregulation of muscle DROSHA supports capillary rarefaction during the development of diabetes in vivo." (PMID 33801773, 2021).
endothelial dysfunction (1 paper, 2021). In vascular diseases, endothelial dysfunction is a systemic pathological state of the endothelium (the inner lining of blood vessels) and can be broadly defined as an imbalance between vasodilating and vasoconstricting substances produced by (or acting on) the endothelium. "We investigated if high glucose conditions could also alter DROSHA expression in the skeletal muscle, a tissue also known to display high glucose-mediated endothelial dysfunction and impaired angiogenic activity." (PMID 33801773, 2021).
glaucoma (1 paper, 2023). Increased pressure in the eyeball due to obstruction of the outflow of aqueous humor. "Genotype association analysis of rs10719 variant in DROSHA with primary open-angle glaucoma and primary angle-closure glaucoma." (PMID 37099569, 2023). "Although studies have reported the genetic association of miRNA biogenesis gene polymorphisms, DICER1 (rs3642330) and DROSHA (rs10719), in a wide variety of human diseases, however, their genetic contribution in glaucoma has not been much investigated." (PMID 37099569, 2023). "The underlying potential mechanism(s) linking DROSHA and DICER1 polymorphisms (rs10719 and rs3742330) to glaucoma pathogenesis is unknown." (PMID 37099569, 2023). "In addition, both the polymorphisms rs3742330 (DICER1) and rs10719 (DROSHA) showed no significant genotype influence on glaucoma-specific clinical indices such as IOP, cup/disk ratio, and the number of antiglaucoma medications." (PMID 37099569, 2023).
Hodgkins lymphoma (1 paper, 2025). A heterogeneous group of malignant lymphoid neoplasms of B-cell origin characterized histologically by the presence of Hodgkin and Reed-Sternberg (HRS) cells in the vast majority of cases. "Our study further expands this understanding by showing that dysregulation of DICER1 and DROSHA is a common feature in hematologic malignancies, not only in myeloid neoplasms but also in lymphoid disorders such as Hodgkin lymphoma." (PMID 41463093, 2025).
Hyperglycemia (1 paper, 2021). An increased concentration of glucose in the blood. "Altogether our data calls for further investigations to fully understand what role the MDM2/DROSHA pathway plays in controlling the maturation of angiomiRs under hyperglycemia." (PMID 33801773, 2021). "Together, our previous and current data support the notion that DROSHA downregulation might be part of the mechanisms that promotes angiostasis during hyperglycemia in MECs." (PMID 33801773, 2021).
Hypertension (1 paper, 2015). The presence of chronic increased pressure in the systemic arterial system. "Furthermore, patients diagnosed with hypertension or DM who carried the DROSHA rs10719 CC genotype showed increased CRC risk, while the XPO5 rs11077 AC+CC genotype led to increased CRC risk in patients with hypertension only." (PMID 26147304, 2015).
Infertility (1 paper, 2025). "Of these, DROSHA, a target gene, is an RNase III enzyme and a cofactor of DGCR8 in the nucleus that mediates the processing of miRNA primary transcript in spermatozoa, and impaired expression caused deficiency in miRNA synthesis and infertility." (PMID 40141332, 2025).
larynx cancer (1 paper, 2015). A primary or metastatic malignant neoplasm involving the larynx. "This is the first report considering the association of the risk of larynx cancer and SNPs of the following polymorphisms: DROSHA (rs6877842), DGCR8 (rs3757, rs417309, and rs1640299), RAN (rs14035), XPO5 (rs11077), DICER1 (rs13078 and rs3742330), and TARBP2 (rs784567)." (PMID 26688807, 2015).
lymph node metastasis (1 paper, 2023). "DROSHA mutation was significantly associated with lymph node metastasis (OR = 1.74, 95% CI = 1.04–2.92, p = 0.035) and poor pathological grade (OR = 2.16, 95% CI = 1.09–4.28, p = 0.027)." (PMID 36672288, 2023). "Patients with DGCR8, DROSHA, and TARBP2 mutations were twice as likely to present with lymph node metastasis." (PMID 36672288, 2023).
medulloblastoma (1 paper, 2025). A malignant, invasive embryonal neoplasm arising from the cerebellum. "The WNT-activated PB harbored a truncating DROSHA mutation characteristic for miRNA-altered PB and a CTNNB1 mutation typically seen in WNT-activated medulloblastomas." (PMID 41291966, 2025).
myeloid neoplasm (1 paper, 2025). Proliferation of myeloid cells originating from a primitive stem cell. "DICER1 and DROSHA transcripts showed a consistent and statistically significant reduction in both AML and MDS compared with controls (p < 0.05), suggesting global downregulation of the early miRNA-processing machinery in myeloid malignancies." (PMID 41463093, 2025).
oncocytoma (1 paper, 2019). "In a pilot experiment by immunohistochemistry on a slide where both oncocytoma and adjacent normal tissue was available decreased level of DROSHA was detected in oncocytoma compared to normal tissue." (PMID 30945144, 2019).
paucibacillary leprosy (1 paper, 2022). "The SNP rs2505901 (pre-miR938) was associated with protection against the development of paucibacillary leprosy, while the SNPs rs639174 (DROSHA), rs636832 (AGO1), and rs4143815 (miR570) were associated with protection against the development of multibacillary leprosy." (PMID 36142557, 2022).
pseudoexfoliation glaucoma (1 paper, 2022). "We investigated the association between DICER1 (rs3742330) and DROSHA (rs10719) polymorphisms and pseudoexfoliation glaucoma (PXG) and related clinical phenotypes in a Saudi cohort." (PMID 35328042, 2022).
renal carcinoma (1 paper, 2022). A carcinoma arising from the epithelium of the renal parenchyma or the renal pelvis. "Furthermore, the CPGs DROSHA and VHL, with putative P/LP variants, are known to be associated with renal cancer." (PMID 35495172, 2022).
thyroid tumor (1 paper, 2019). A benign or malignant neoplasm affecting the thyroid gland. "The mutational status in the hot spot regions of DICER1, DROSHA, TARBP2, DGCR8 and the most commonly affected genes in thyroid tumors was investigated on both tumor and paired normal tissues." (PMID 30956758, 2019).
tuberculosis (1 paper, 2022). A chronic, recurrent infection caused by the bacterium Mycobacterium tuberculosis. "In the present study, we examined the possible association of polymorphisms in miRNA and DROSHA genes with tuberculosis susceptibility in the Brazilian Amazonian population." (PMID 35309115, 2022).